RNU6-1150P (RNA, U6 small nuclear 1150, pseudogene)
Gene: Small nuclear RNA gene on chromosome 21 (43,996,322 to 43,996,420, reverse strand). Ensembl gene ENSG00000252606.
Homologues: Orthologues: chimpanzee U6 (100% identical), macaque U6 (90% identical), mouse Gm25578 (75% identical), rabbit U6 (69% identical), rat LOC120099418 (67% identical). Paralogues in human: RNU6-725P (95% identical), RNU6-641P (82% identical), RNU6-1124P (81% identical), RNU6-338P (81% identical), RNU6-664P (81% identical), RNU6-1075P (80% identical), RNU6-1227P (80% identical), RNU6-1316P (80% identical), RNU6-140P (80% identical), RNU6-25P (80% identical), RNU6-29P (80% identical), RNU6-35P (80% identical), and 1287 more.